CLPX (caseinolytic mitochondrial matrix peptidase chaperone subunit X)
Diseases named in the same sentence as CLPX in open-access papers:
CLPX is named in the same sentence as 36 diseases in open-access papers, as found by Europe PMC text mining. Sharing a sentence is not in itself a finding about the gene and the disease. The quoted sentences say what the papers report.
erythropoietic protoporphyria (3 papers, 2022 to 2025). A rare congenital metabolic disorder characterized by an inborn error of porphyrin-heme biosynthesis. "A naturally occurring CLPX variant associated with an erythropoietic disorder has been reported in humans; a heterozygous missense variant in CLPX, which partially inactivates the protein by inhibiting ClpXP complex formation, has been associated with erythropoietic protoporphyria in a human family." (PMID 41300811, 2025). "Although mutations in ClpX also lead to the blood disorder erythropoietic protoporphyria, the role of the human ALAS2-ClpX interaction is still being elucidated." (PMID 35093382, 2022). "However, in any of the protoporphyrias, pathological variants in the ALAS2, CLPX or FECH genes lead to the accumulation of excess PPIX in the maturating erythroblasts in the bone marrow." (PMID 39011756, 2025).
skin abscess (3 papers, 2022 to 2025). "In contrast, clpX and clpP deletion mutants of S. aureus are highly attenuated in the skin abscess model, likely due to their control of several major staphylococcal virulence factors." (PMID 40208051, 2025). "In addition, in a mouse skin abscess model, the inactivation of clpX and clpP completely reduced the formation of abscesses." (PMID 35369527, 2022).
anemia (2 papers, 2021 to 2025). A reduction in the number of red blood cells, the amount of hemoglobin, and/or the volume of packed red blood cells. "CLPX also regulates heme synthesis—variants in this gene or related genes have been associated with erythropoietic protoporphyria 2 and anemia in humans." (PMID 41300811, 2025). "The myocardial fibrosis and focal cardiomyocyte necrosis seen in the case dog may reflect secondary hypoxic injury associated with severe anemia, although a direct contribution of the CLPX variant to cardiac pathology cannot be excluded." (PMID 41300811, 2025). "However, the identification of the CLPX variant raises the possibility of mitochondrial dysfunction being responsible for the anemia." (PMID 41300811, 2025). "Our studies reveal that CLPX mutations may cause anemia and porphyria via dysregulation of ALAS, FECH, and PPOX activities, as well as of iron metabolism." (PMID 34280433, 2021). "This theory is supported by findings that CLPX knockout in murine erythroid cells reduced hemoglobin and heme synthesis, and that CLPX knockout in zebrafish similarly resulted in anemia." (PMID 41300811, 2025). "Given the gene’s high evolutionary conservation and known role in mitochondrial protein homeostasis, this finding may have implications for understanding CLPX-related neurodegeneration and anemia in both veterinary and human medicine." (PMID 41300811, 2025). "We describe a CLPX variant that is associated with an SCA phenotype and nonregenerative anemia and provide a detailed characterization of the pathology." (PMID 41300811, 2025).
allergic rhinitis (1 paper, 2025). Inflammation of the nasal mucous membranes caused by an IgE-mediated response to external allergens. "As both CLPX and MRPL53 regulate fundamental cellular functions, they are likely to have some influence on the pathophysiology of allergic rhinitis." (PMID 39913623, 2025).
atrial fibrillation (1 paper, 2025). A disorder characterized by an electrocardiographic finding of a supraventricular arrhythmia characterized by the replacement of consistent P waves by rapid oscillations or fibrillatory waves that vary in size, shape and timing and are accompanied by an irregular ventricular response. "The WMH TWAS also identified genes associated with AD (ARMS2), atrial fibrillation (NEURL and GJC1), innate immunity (EFTUD2), and apoptosis and neurodevelopment (PDCD7, FBXO31, and ClpX)." (PMID 40141087, 2025).
breast adenocarcinoma (1 paper, 2016). "In addition, silencing of ClpP or ClpX minimally reduced proliferation of non-metastatic breast adenocarcinoma MCF-7 cells, and non-tumorigenic breast epithelial MCF-10A cells were not affected." (PMID 27389535, 2016).
deafness (1 paper, 2023). An inherited or acquired condition characterized by the complete loss of the ability to hear from one or both ears. "This provides mechanistic detail in the understanding of PRLTS3 pathogenesis where CLPX is in excess, and progressive deafness is due to mitoribosomal translation problems." (PMID 38139332, 2023).
diffuse intrinsic pontine glioma (1 paper, 2023). A neuroglial tumor that arises from the middle portion of the brain stem. "ClpX is suppressed upon ONC212 treatment in pancreatic cancer cells and in diffuse intrinsic pontine glioma (DIPG) cells treated with ONC206." (PMID 36675163, 2023).
glioblastoma (1 paper, 2025). The most malignant astrocytic tumor (WHO grade IV). "We therefore applied the combination of ONC201, TMZ and RT to SNB19, T98G, U138, and U251 glioblastoma cells and performed Western blot analysis of the expression of PARP, ATF4, LC3B and ClpX." (PMID 40145650, 2025).
Infertility (1 paper, 2016). "Accumulation of CLPX, mtDNA, and inflammatory factors in tissues have been observed in mice mutants due to CLLP loss of function leading to infertility, hearing loss, and growth retardation." (PMID 27087618, 2016).
leukemia (1 paper, 2021). A malignant (clonal) hematologic disorder, involving hematopoietic stem cells and characterized by the presence of primitive or atypical myeloid or lymphoid cells in the bone marrow and the blood. "Therefore, the protein expression of the ClpX chaperone and ClpP were assessed in different leukemia cell lines." (PMID 34045646, 2021).
Lyme borreliosis (1 paper, 2016). "Housekeeping loci that were used successfully for multilocus sequence typing of Lyme borreliosis group spirochetes and relapsing fever spirochetes included clpA, clpX, nifS, pepX, pyrG, recG, rplB and uvrA." (PMID 27031729, 2016).
neuroblastoma (1 paper, 2023). Neuroblastoma (NB) is the most common solid, extracranial childhood tumor. "Firstly, we observed a significant increase in ClpP and ClpX expression in immature and mature ganglion cells as compared to more malignant neuroblasts and less malignant Schwannian-stroma-dominant cell types in human neuroblastoma tissues." (PMID 36675163, 2023).
neutropenia (1 paper, 2022). A decrease in the number of neutrophils found in the blood. "Dysfunction of the three AAA+ unfoldases CLPX, CLPB, and LONP1 causes distinctive features in peripheral tissues such as deficient heme biosynthesis, neutropenia, and collagen networks, respectively." (PMID 35954215, 2022).
pancreatic cancer (1 paper, 2022). "ClpX, the ATPase subunit of the ClpXP complex, was previously observed to decline after 24 h of ONC212 treatment in pancreatic cancer models." (PMID 35929764, 2022).
Perrault syndrome (1 paper, 2023). Perrault syndrome (PS) is characterized by the association of ovarian dysgenesis in females with sensorineural hearing impairment. "Thus, the RNA granule might become involved in Perrault syndrome only via the off-target effects of excess CLPX." (PMID 38139332, 2023).
pneumonia (1 paper, 2026). An acute, acute and chronic, or chronic inflammation focally or diffusely affecting the lung parenchyma, caused by an infection in one or both of the lungs (by bacteria, viruses, fungi, or mycoplasma.). "In a murine pneumonia model, loss of ClpX impairs infection of both hvKp and cKp." (PMID 41616254, 2026).
prostate carcinoma (1 paper, 2016). A carcinoma that arises from epithelial cells of the prostate gland. "In contrast, knockdown of ClpX or ClpP significantly reduced Complex II activity in PC3 cells as well as other prostate cancer cell types, including C4-2 and DU145." (PMID 27389535, 2016). "siRNA silencing of ClpP or ClpX resulted in increased total cellular superoxide production in prostate cancer cells." (PMID 27389535, 2016).
sideroblastic anemia (1 paper, 2025). "Variants in the ALAS2 gene, encoding ALAS2 (regulated by CLPX) can cause hereditary sideroblastic anemia in humans." (PMID 41300811, 2025).
skin infection (1 paper, 2020). An inflammatory process affecting the skin, caused by bacteria, viruses, parasites, or fungi. "Mutagenesis experiments also indicated a role of clpX in regulation of autolysis, cell division, and virulence in skin infections." (PMID 33293382, 2020).
thyroid cancer (1 paper, 2025). "Our results showed that both MRPL13 and CLPX are highly associated with the ribosome signaling pathway, while MRPS30 is highly correlated with the thyroid cancer signaling pathway and showed high expression." (PMID 39913623, 2025).
infection (13 papers, 2017 to 2026). The state of being infected such as from the introduction of a foreign agent such as serum, vaccine, antigenic substance or organism. "The PCA revealed, for the second and third components, an entanglement of the effect of ClpX deficiency and infection-relevant stresses." (PMID 41247024, 2025). "Intriguingly, in our cell culture infection experiments, the ClpX-deficient strains showed reduced intracellular replication during the early stage of infection and a high proportion of intracellularly persisting bacterial cells." (PMID 41247024, 2025). "Here, we indicate that ClpXP contributes to virulence by showing that pneumococcus carrying a ClpX variant that cannot associate with ClpP displays reduced lethality in the G. mellonella larvae model of infection." (PMID 40407370, 2025). "These include mutations in purA, purB, and clpX, which have been shown to be important in various models of infection (12, –, 14)." (PMID 34101490, 2021). "Since ClpX modulates virulence gene expression via SpxA1 and SpxA2, we assessed the pathogenic potential of these mutants during infection." (PMID 28351920, 2017). "As demonstrated by the proteomic profiles under infection-relevant conditions, a plethora of proteins, which are associated with virulence and bacterial fitness, are dysregulated with regard to their abundance in the ClpX-deficient strain." (PMID 41247024, 2025). "Next, we tested the virulence of the two clpX mutant strains in the Galleria mellonella larvae model of infection." (PMID 40407370, 2025). "It’s intriguing to note that during the early infection when intracellular ROS was accumulating, the elevation of lon transcript level corresponds with vapBC operons, but the transcription of clpX was unaltered." (PMID 40737303, 2025). "Previously, a decline of ClpX protein levels has been observed in long-term intracellular S. aureus, supporting the strategy of persister formation during infection." (PMID 41247024, 2025). "With our proteomics approach and in-depth data analysis, we provide a resource for global insight into ClpX-dependent adaptation of S. aureus physiology under infection-relevant conditions." (PMID 41247024, 2025). "Accordingly, this analysis provides new insights into ClpX’s role in physiological adaptation to changes related to the niches of S. aureus during infection processes and will serve as a valuable resource for further research." (PMID 41247024, 2025). "In a mouse infection model, mice challenged with the Δ-ClpX strain exhibited prolonged survival times compared to those challenged with the wild-type and complemented strains." (PMID 40793820, 2025). "We demonstrated that ClpX plays a decisive role in S. aureus pathophysiology and is critical for protein homeostasis of a plethora of infection-relevant physiological aspects." (PMID 41247024, 2025). "Our study highlighted that ClpX is involved in the iron and oxygen limitation response as a central aspect of bacterial fitness in infection processes." (PMID 41247024, 2025). "Through this intricate regulatory mechanism, ClpP and ClpX are integral to the pathogenicity of S. aureus, ensuring that virulence factors are expressed in a coordinated manner to optimize infection." (PMID 40588743, 2025). "The association of reduced virulence with ClpX depletion is supported by the observation that the D39V ΔclpX czcD::clpX strain partly regained lethality when pre-grown in the presence of ZnCl2 to allow for ectopic ClpX expression at the time of infection (T = 0)." (PMID 40407370, 2025). "Given that Δ-ClpX exhibited distinct phenotypes during serum resistance and biofilm production compared with wild-type strain, we further investigated the role of ClpX in the infection process of G. parasuis by evaluating the ability of test strains to withstand various culture conditions." (PMID 40793820, 2025).
infection (continued). "The specific role of ClpX in enabling G. parasuis to overcome these stresses and facilitate infection has not been previously elucidated, and the underlying mechanisms remain to be determined." (PMID 40793820, 2025). "Although a few studies on ClpX-dependent changes in the S. aureus proteome have been carried out (e.g., references 26, 79]), there is a lack of state-of-the-art proteomic profiles of a ClpX-deficient S. aureus strain under infection-relevant conditions." (PMID 41247024, 2025). "In addition, we demonstrate the importance of ClpX in S. aureus bacterial fitness in infection processes." (PMID 41247024, 2025). "The high proportion of persisting cells raises the question of whether reduced ClpX levels support persister formation and recurring infection processes." (PMID 41247024, 2025). "Similarly, ClpX-driven effects on intracellular replication during short-term infections were previously reported." (PMID 41247024, 2025). "In addition, the member of the positive ClpX modulon staphopain A is an extracellular protease that degrades several host proteins and shapes the infection process." (PMID 41247024, 2025). "Four of these genes, clpX, purH, mntA, and htrA, had been constructed in a fully-virulent strain of B. anthracis (pXO1+, pXO2+) and shown to be attenuated in mammalian infection models so we were confident these represented true virulence determinants of B. anthracis." (PMID 31681636, 2019). "ClpX-dependent regulation exacerbates disease by intensifying neutrophil dysregulation, excessive NET accumulation, and impaired resolution of infection in an already compromised host environment." (PMID 42262120, 2026). "Here, we investigated how the GAS ClpX-dependent regulatory pathway (CDRP), a global virulence regulator, interacts with diabetic immune dysfunction to shape infection outcomes." (PMID 42262120, 2026). "Prior to infection, the D39VΔclpX czcD::clpX strain was grown with or without 200 μM ZnCl2 to allow for determining the role of ClpX in virulence." (PMID 40407370, 2025). "Our previous findings demonstrated that the CI-NTD cleavage fragment alone retained repressor functionality and could block prophage induction and infection in the absence of ClpX." (PMID 37852980, 2023).
tumor (4 papers, 2016 to 2025). "The IRT triple combination not only reduces tumor cell proliferation, but also induces more apoptosis, and inhibits ClpX to unleash mitochondrial ClpP in short-term biomarker studies." (PMID 40145650, 2025). "In a first series of experiments, knockdown of ClpP or ClpX partially reduced tumor cell proliferation and inhibited colony formation, a marker of tumorigenicity." (PMID 27389535, 2016). "The effect of ClpXP silencing on tumor cell proliferation was cell-type-specific and more pronounced after knockdown of ClpP compared to ClpX." (PMID 27389535, 2016). "siRNA knockdown of ClpP or ClpX inhibited directional PC3 cell migration in a wound closure assay, and suppressed tumor cell invasion across Matrigel-coated Transwell inserts." (PMID 27389535, 2016). "ClpP agonists can hydrolyze substrate protein such as respiratory chain-related protein regardless of ClpX, which is reported as a novel tumor treatment method." (PMID 40395852, 2025). "Re-expression of Cav1 in these settings restored Akt phosphorylation and rescued the defect of tumor cell invasion after ClpP, but not ClpX knockdown." (PMID 27389535, 2016). "Although this proteasome-like arrangement is conserved in mammalian cells, the data presented here suggest that the ClpP and ClpX subunits may not have completely overlapping function(s) in tumor mitochondria, especially with respect to Akt activation and Cav1-dependent tumor cell motility." (PMID 27389535, 2016).
blood disorder (3 papers, 2021 to 2023). "The implication of ClpP and ClpX in neuronal differentiation and maturation in NB seems contrary to previous studies reporting that ClpXP is overexpressed in hematologic malignancies and solid tumors, and is necessary for the viability of a subset of tumors." (PMID 36675163, 2023).
cancer (2 papers, 2020 to 2025). A tumor composed of atypical neoplastic, often pleomorphic cells that invade other tissues. "In summary, ClpP and ClpX are stable and ubiquitously expressed to varying degrees in human healthy tissues and cancers, supporting their value as therapeutic targets in malignancies with heightened mitochondrial stress or metabolic vulnerability." (PMID 41155556, 2025). "While fewer studies have examined the importance of ClpX for the viability of malignant cells, it is believed that the results with ClpP are a surrogate for the activity of the ClpXP holoenzyme and inhibiting ClpX in cancer would produce similar results." (PMID 33037181, 2020). "Like ClpP, ClpX expression is not prognostic in any analyzed cancer type, reinforcing its role as a conserved component of mitochondrial proteostasis." (PMID 41155556, 2025). "To date, the majority of studies in cancer have focused on targeting ClpP and have not extensively investigated ClpX." (PMID 33037181, 2020). "In addition, ClpX expression in cancer has not been widely reported." (PMID 33037181, 2020).
metabolic disorders (1 paper, 2021). "CLPX mutations contribute to metabolic disorders in human patients and animal models, and CLPX regulates heme synthesis in erythroid cells by control of mitochondrial heme synthesis and iron utilization." (PMID 34280433, 2021). "Unraveling the complexities of CLPX function will be key for designing therapies for metabolic diseases and mitochondriopathies." (PMID 34280433, 2021).
CLPX also shares sentences with these, for which no sentence is quoted: abscesses (1 paper); bacterial infections (1); erythropoietic protoporphyria 2 (1); genetic disorders (1); Hyperkeratosis (1); Insulin resistance (1); Obesity (1); porphyria (1); prostate adenocarcinoma (1); Spinocerebellar Ataxia (1).